LOXL4 (lysyl oxidase like 4)
Diseases named in the same sentence as LOXL4 in open-access papers (continued):
Sharing a sentence is not in itself a finding about the gene and the disease.
hepatocellular carcinoma (18 papers, 2013 to 2025). A malignant tumor that arises from hepatocytes. "Likewise, LOXL4 expression is found to be upregulated in hepatocellular carcinoma, and is associated with enhanced tumor cells invasiveness and tumor metastasis to lungs." (PMID 35682926, 2022). "Many studies have shown that LOXL4 is overexpressed and promotes tumor progression in some human malignancies, such as hepatocellular carcinoma and gastric cancer." (PMID 39286023, 2024). "Exosomes also use lysine oxidase-like 4 (LOXL4) to promote invasion and metastasis of hepatocellular carcinoma cells, and intracellular LOXL4 activates the FAK/Src pathway to promote cancer cell migration." (PMID 36275738, 2022). "LOXL4 is reported to promote the proliferation and metastasis of gastric cancer, as well as hepatocellular carcinoma invasion and metastasis." (PMID 35682926, 2022). "Lysyl oxidase-like 4 (LOXL4) LOXL4 is commonly upregulated in hepatocellular carcinoma (HCC) tissues." (PMID 34830956, 2021). "Donor hepatocellular carcinoma (HCC)-derived exosomes transferred Lysyl-oxidase-like 4 between HCC cells to human umbilical vein endothelial cells (HUVECS), where they promoted angiogenesis and cell migration in a paracrine manner." (PMID 34677212, 2021). "Lysyl oxidase-like 4 (LOXL4) has been found to be dysregulated in several human malignancies, including hepatocellular carcinoma (HCC)." (PMID 30704479, 2019). "A recent study found that LOXL4 was downregulated in hepatocellular carcinoma, and this downregulation was closely correlated with worse clinical outcomes." (PMID 28060764, 2017). "A candidate gene would be LOXL4, a target of TGF-β1 found to cause reduction in TGFβ1-mediated cell motility of hepatoma cells." (PMID 23408952, 2013). "In preclinical models of human hepatocellular carcinoma, high LOXL4 expressing macrophages have an immunosuppressive function via an interferon (IFN)-mediated signal transducer and activator of the transcription (STATs)-dependent PD-L1 activation on CD8+ T cells." (PMID 35205728, 2022). "Interestingly, it was observed that hepatocellular carcinoma-derived exosomes transferred LOXL4 between hepatocellular carcinoma cells." (PMID 35682926, 2022). "Lysyl oxidase-like 4 (LOXL4) is highly expressed in hepatocellular carcinoma (HCC)." (PMID 37907962, 2023). "Our previous studies have shown that miR-193a-3p is involved in multi-drug resistance in both hepatocellular carcinoma and bladder cancer via the repression of different target genes, including SRSF2, PLAU, HIC2 and LOXL4." (PMID 27056900, 2016).
bladder cancer (10 papers, 2014 to 2025). "In addition to a new mechanistic insight, our results provide a set of the essential genes in this newly identified miR-193a-3p/LOXL4/Oxidative Stress axis as the diagnostic targets for a guided anti-bladder cancer chemotherapy." (PMID 25311867, 2014). "However, in lung cancer and bladder cancer, LOXL4 may function as a tumour suppressor, as LOXL4 deficiency enhances cancer cell proliferation and metastasis." (PMID 39247609, 2024). "The mechanism by which miR-193a-3p enhanced drug resistance was shown to be the inhibition of Serine/arginine-rich splicing factor 2 (SRSF2) and lysyl oxidase-like 4 (LOXL4) expression in bladder cancer cells." (PMID 36685879, 2022). "A previous study indicates that another DNMT inhibitor 5-aza-2′-deoxycytidine also can epigenetically upregulates LOXL4 transcription in bladder cancer cells." (PMID 30728460, 2019). "LOX and LOXL2 reportedly promote kidney carcinoma tumorigenesis, while LOX, LOXL1 and LOXL4 suppress bladder cancer growth." (PMID 29732010, 2018). "We further demonstrated that lysyl oxidase-like 4 (LOXL4) gene [GenBank: NM_032211.6] is a direct target of miR-193a-3p and executes the former’s impact on bladder cancer chemoresistance." (PMID 25311867, 2014). "Conversely, studies have suggested that the overexpression of LOXL4 may inhibit human bladder cancer cells by counteracting the Ras/ERK signalling pathway." (PMID 39247609, 2024). "Additionally, microRNA (miR)-193a-3p modulates oxidative stress (OS) signaling to promote multi-drug chemoresistance in bladder cancer by inhibiting LOXL4 expression." (PMID 29732010, 2018). "Furthermore, low expression levels of LOXL4 and SRSF2 – genes regulated by miR-29b-3p and miR-193a-3p – have been associated with inhibited apoptosis and enhanced multi-drug resistance in bladder cancer." (PMID 40061896, 2025). "The miR-193a-3p/LOXL4/OS axis may be a new target for anti-bladder cancer chemotherapeutics." (PMID 29732010, 2018).
gastric cancer (9 papers, 2015 to 2025). A primary or metastatic malignant neoplasm involving the stomach. "Studies in gastric cancer cell lines show that LOXL4 promotes cell proliferation, migration, and invasion through the FAK/Src pathway." (PMID 40906383, 2025). "Several studies have reported changes in LOX, LOXL1, LOXL2, LOXL3, and LOXL4 expression in gastric cancer." (PMID 40906383, 2025). "Studies have reported that the expression of LOX family members LOXL1, LOXL3, and LOXL4 is related to distant metastasis of gastric cancer." (PMID 34595188, 2021). "LOXL4 was significantly up-regulated in gastric carcinoma tissues, and this over-expression is significantly correlated with tumor size, depth of tumor invasion, lymph node metastasis, higher TNM stages and poor prognosis." (PMID 35126449, 2021). "Our previous study has showed that LOXL4 promotes proliferation and metastasis of gastric cancer via activating the FAK/Src pathway." (PMID 30704479, 2019). "LOXL4 is expressed in head and neck squamous cell carcinoma and gastric cancer cell lines, and upregulation of LOXL4 significantly correlates with tumor stage and lymph node metastases." (PMID 26579497, 2015). "In gastric cancer, it has been described that LOXL4 expression is upregulated in biopsies." (PMID 40906383, 2025). "LOXL4 promotes proliferation, migration, and invasion in gastric cancer cell lines in vitro." (PMID 26579497, 2015). "Other researchers and we have demonstrated that the expression of LOXL4 is upregulated in several human cancers, including head and neck squamous cell carcinoma (HNSCC), laryngeal squamous cell carcinoma, and gastric cancer." (PMID 30704479, 2019). "For instance, our previous study has showed that LOXL4 promotes gastric cancer progression via activating the FAK/Src pathway; LOXL4 knockdown enhances tumor growth and lung metastasis through collagen-dependent extracellular matrix changes in triple-negative breast cancer." (PMID 30704479, 2019). "In a cohort study involving 597 patients treated with primary treatment for gastric cancer, the OS with positive expression of LOXL1, LOXL3, or LOXL4 was significantly shorter than with negative LOXL4 expression." (PMID 41250755, 2025).
triple-negative breast carcinoma (8 papers, 2017 to 2024). An invasive breast carcinoma which is negative for expression of estrogen receptor (ER), progesterone receptor (PR), and human epidermal growth factor receptor 2 (HER2). "LOXL4’s deletion has been found to enhance tumor growth and metastasis in triple-negative breast cancer through ECM-related mechanisms." (PMID 37777759, 2023). "LOXL4 knockdown enhances tumor growth and lung metastasis through collagen-dependent extracellular matrix changes in triple-negative breast cancer." (PMID 37240298, 2023).
liver cancer (6 papers, 2019 to 2024). An epithelial or non-epithelial malignant neoplasm that arises from the liver. "Loading exosomes with lysyl oxidase-like 4 (LOXL4) produced by liver cancer cells promotes macrophage PD-L1 expression, mediated by interferon and STATs." (PMID 38195554, 2024). "LOXL4 regulates tumor metastasis through the FAK/Src pathway to regulate liver cancer angiogenesis and cell-matrix adhesion, resulting in poor prognostic effects." (PMID 33564309, 2021). "To define the clinical relevance of LOXL4 in liver cancer patient survival, we analyzed human liver cancer tissues by immunohistochemistry (IHC)." (PMID 30728460, 2019). "However, LOXL4 plays specific roles in the proliferation and metastasis of cells in certain malignancies, such as gastric and liver cancer." (PMID 34393991, 2021). "Currently, how LOXL4 functions in liver cancer is not understood." (PMID 30728460, 2019).
breast tumor (5 papers, 2015 to 2024). "Lysyl oxidase, LOXL2, or LOXL4 expression in the primary breast tumor leads to pre-metastatic deposition of collagen I in the lungs of mice, favoring the formation of metastases in the lungs." (PMID 26539408, 2015). "In addition, they described that HIF-1α plays a critical role in collagen biogenesis in breast tumors by upregulating the expression of P4HA1, P4HA2, PLOD1, and PLOD2 hydroxylases as well as the lysyl oxidase family members LOX, LOXL2, and LOXL4." (PMID 37686617, 2023).
glioma (4 papers, 2020 to 2025). A benign or malignant brain and spinal cord tumor that arises from glial cells (astrocytes, oligodendrocytes, ependymal cells). "The results indicated that members of the LOX family, including LOX, LOXL1, LOXL2, LOXL3, and LOXL4, exhibited high expression levels in glioma cells in comparison to normal human glial cell lines Heb as well as glioblastoma cell lines T98G and LN-229." (PMID 40270974, 2025). "Loxl3 can promote tumor cell invasion in GBM, and Loxl4 is recognized as a stemness-related prognostic biomarker in glioma." (PMID 38978755, 2024). "Considering some previous investigations illustrating that LOXs, especially, LOX, LOXL1, and LOXL4 are closely associated with immunity, finally contributing to tumor progression, we would like to explore whether LOXs expressions were correlated with glioma immunity." (PMID 36160460, 2022). "Finally, RT-qPCR and Western blot analysis were carried out to validate the mRNA and protein levels of LOXs including LOX, LOXL1, LOXL2, LOXL3, and LOXL4 in glioma cells (T98G and A172) and the normal cell line (HEB)." (PMID 36160460, 2022). "In addition, all of them except LOXL4 were related to the OS of patients with recurrent glioma significantly." (PMID 32725165, 2020). "Additionally, this in silico study also identifies three novel prognostic biomarkers (F2RL2, CLCNKA and LOXL4) for glioma patients." (PMID 32725165, 2020). "Additionally, we also identified three novel prognostic biomarkers (F2RL2, CLCNKA and LOXL4) for glioma patients in silico." (PMID 32725165, 2020). "Besides other eight reported biomarkers of glioma, we found that F2RL2, CLCNKA and LOXL4 were first identified as prognostic biomarkers for glioma." (PMID 32725165, 2020). "Compared with CLCNKA and LOXL4, F2RL2 was specifically applied in all grades of primary glioma, revealing its prognostic role in primary glioma." (PMID 32725165, 2020). "The results shown in CGGA-325 dataset revealed that the glioma patients with the high levels of all members of LOX family including LOX, LOXL1, LOXL2, LOXL3, and LOXL4 displayed poor prognosis with the MST of only 34.3, 31, 31, 35.3, and 34.8 months, respectively." (PMID 36160460, 2022). "The results indicated that the mRNA and protein expressions of LOX, LOXL1, LOXL2, and LOXL3 were significantly upregulated in these glioma cells than in HEB cell line while the expressions of LOXL4 at mRNA and protein level were not determined in these cell lines (data not shown)." (PMID 36160460, 2022). "F2RL2, CLCNKA and LOXL4 are novel prognostic biomarkers for glioma which have not reported before." (PMID 32725165, 2020). "Finally, the 11 prognostic SRGs in the final multivariate model were validated by the CGGA data and we found three novel prognostic biomarkers (F2RL2, CLCNKA and LOXL4) for glioma that have not been reported before." (PMID 32725165, 2020).
head and neck squamous cell carcinoma (4 papers, 2015 to 2023). A squamous cell carcinoma that arises from any of the following anatomic sites: lip and oral cavity, nasal cavity, paranasal sinuses, pharynx, larynx, and salivary glands. "It has been reported that LOXL4 monoclonal antibody (LOXL4-mAb) effectively prevents the growth of head and neck squamous cell carcinoma (HNSCC) cells in vivo." (PMID 37091157, 2023). "LOXL4 encodes a copper-dependent amine oxidase that is involved in the formation of crosslinks in collagens and elastin and is a potential drug target for the treatment of head and neck squamous cell carcinoma, where it is differentially expressed between tumor and normal tissue." (PMID 32727620, 2020).
melanoma (4 papers, 2018 to 2025). A malignant, usually aggressive tumor composed of atypical, neoplastic melanocytes. "On the contrary, LOX and especially LOXL2, LOXL3, and LOXL4 were found to be upregulated in several human melanoma cell lines, and LOX inhibitor B-aminopropionitrile inhibited the invasive growth of these cells particularly when co-cultured with fibroblasts in Matrigel." (PMID 30701028, 2018). "With regard to the genes specifically up-regulated in the MCSP CTC fraction, the majority have been involved in metastasis (LOXL4, ST6GALNAC2, PYGL), tumour growth (PLK2, CYSTM1, GLUL), and/or melanoma biology (SEC31A, WIPI1, SKP1)." (PMID 30769764, 2019).
diabetes (3 papers, 2017 to 2023). "In addition, our studies found that TSP1 targets included: TAGLN, a regulator of angiogenesis, LOXL4, a contributor to the vascular permeability in diabetes, types of collagen (COL4A1 and COL8A1) that influence angiogenesis plus THSB1 an inhibitor of angiogenesis." (PMID 36949528, 2023). "Signature genes included previously reported beta-specific genes like NKX6-1, DLK1, and ADCYAP1 (right) and alpha cell–specific genes like IRX2, LOXL4, and DPP4, a cell surface receptor and diabetes drug target." (PMID 27864352, 2017).
colorectal cancer (2 papers, 2020 to 2022). A primary or metastatic malignant neoplasm that affects the colon or rectum. "Furthermore, Lysyl oxidase-like 4 (LOXL4) expressing neutrophils that infiltrated colorectal cancer liver metastases were found to identify patients that were resistant to anti-angiogenic therapy." (PMID 32849639, 2020).
head and neck cancer (2 papers, 2022 to 2024). A primary or metastatic malignant neoplasm affecting the head and neck. "One previous report has shown that anti-LOXL4 antibody effectively prevents head-and-neck cancer progression." (PMID 38595825, 2024). "Lysyl oxidase-like 4 is an amine oxidase from the lysyl oxidase family that was previously shown to be overexpressed in head and neck cancer and upregulated in response to hypoxia." (PMID 33757755, 2022).
liver fibrosis (2 papers, 2019 to 2024). "LOX proteins (LOX, LOXL1, LOXL2, LOXL3, and LOXL4) are extracellular copper‐dependent enzymes and have been identified as potential therapeutic targets in liver fibrosis." (PMID 38853023, 2024).
lung fibrosis (2 papers, 2018 to 2021). "In addition, they also found increased expression of Loxl2, Loxl3, and Loxl4 in whole lung tissue from pulmonary fibrosis mouse models using gene expression assays at day 14 post-bleomycin." (PMID 34395518, 2021).
ovarian carcinoma (2 papers, 2020). A malignant neoplasm originating from the surface ovarian epithelium. "Sebban et al57 showed that LOXL4 was highly expressed in ovarian cancer following chemotherapeutic treatment with both paclitaxel and platinum compounds." (PMID 33058284, 2020). "Moreover, LOXL4 mRNA overexpression was related to lower OS and PFS in serous and grade II + III ovarian carcinoma patients and poor PFS in endometrioid ovarian carcinoma patients." (PMID 33058284, 2020). "There has been no research studying the role of LOXL4 in ovarian carcinoma." (PMID 33058284, 2020).
abdominal aortic aneurysm (1 paper, 2021). Enlargement and ballooning of the vessel that supplies arterial blood to the abdomen, pelvis and legs. "This study shows that Loxl4 abrogation did not exaggerate angiotensin II-induced thoracic or abdominal aortic aneurysm in mice by using the angiotensin II-induced TAA or AAA mouse model system." (PMID 33807332, 2021). "We found that abrogation of Loxl4 did not induce a more severe thoracic or abdominal aortic aneurysm compared with the wild-type C57BL/6J mice." (PMID 33807332, 2021).
adolescent idiopathic scoliosis (1 paper, 2011). A scoliosis with no known cause arising in adolescent. "We hypothesized that common polymorphisms in the five human lysyl oxidase genes (LOX, LOXL1, LOXL2, LOXL3, and LOXL4) may be associated with the phenotype of adolescent idiopathic scoliosis." (PMID 21740577, 2011).
aortic aneurysm (1 paper, 2021). A ruptured aneurysm located in the wall of the proximal portion of the descending aorta proceeding from the arch of the aorta. "Our results suggest that LOXL4 may not play a major role in the development of angiotensin II-induced aortic aneurysm." (PMID 33807332, 2021).
astrocytomas (1 paper, 2022). "LOXL1, LOXL2, LOXL3, and LOXL4 expression levels were also found to increase progressively in astrocytomas from grades 2 to 4, proving highest in GBM, and significantly higher relative to non-neoplastic brain tissue." (PMID 36076905, 2022). "Gene expression analysis by quantitative real-time PCR (RT-qPCR) for LOX, LOXL1, LOXL2, LOXL3, and LOXL4 showed increased expression levels in astrocytoma samples compared to non-neoplastic (NN) samples." (PMID 36076905, 2022).
bladder tumor (1 paper, 2016). "However, over expression of the LOX-related enzymes, LOXL1 and LOXL4, in 5637 cells antagonized Ras activation and reduced Erk phosphorylation, suggesting that these enzymes function to suppress bladder tumor growth." (PMID 26968815, 2016).